AR (androgen receptor)
Diseases named in the same sentence as AR in open-access papers (continued):
Sharing a sentence is not in itself a finding about the gene and the disease.
prostate carcinoma (continued). "The approval of PLUVICTO® in March 2022 for patients with metastatic castration-resistant prostate cancer who have undergone prior treatments, including androgen receptor pathway-targeting agents and taxane-based chemotherapy, represents a significant advancement." (PMID 40724999, 2025). "PC-3 and DU-145, both prostate cancer cell lines that are androgen receptor-independent." (PMID 40806750, 2025). "Our results coincide with previous studies where increased stiffness was linked to metastasis and EMT in AR-negative (AR-independent) prostate cancer cell lines, thus supporting the importance of matrix stiffness in the progression of prostate cancer." (PMID 40115748, 2025). "AR is crucial in the development and progression of most prostate cancer cases." (PMID 40013333, 2025). "ARHGAP21 silencing in LNCaP prostate cancer cells decreases AR transcriptional levels." (PMID 41301045, 2025). "SCNC is rare in primary PCa, whereas about 10–17% of patients with metastatic androgen deprivation-resistant prostate cancer (ARPC) have been reported to develop treatment-related SCNC (t-SCNC) after receiving second-generation androgen receptor pathway inhibitors (ARPIs)." (PMID 40723267, 2025). "Finally, in prostatic cancers, preclinical evidence has pointed to a ‘BRCAness’ phenotype induced by androgen receptor (AR) signaling inhibition." (PMID 39927794, 2025). "To determine whether REV-ERBα is directly regulated by androgen signaling, we treated AR-positive prostate cancer cells (16D and C4-2B) with increasing concentrations of dihydrotestosterone (DHT)." (PMID 41231955, 2025). "Thus, the immunological landscape of prostate cancer presents a formidable challenge owing to its low immunogenicity, extensive immunosuppression, and intricate AR-driven biology." (PMID 40227610, 2025). "The role of AR in the initiation and development of prostate cancer is well established." (PMID 40336533, 2025). "CDK 4/6 inhibitor blocks proliferation in an RB- and cyclin D-dependent manner in preclinical prostate cancer models, raising the hypothesis that co-targeting AR and cell cycle with CDK 4/6 inhibitor could improve outcomes in patients with mHSPC." (PMID 39796175, 2025). "Capsaicin, isolated from Capsicum species, inhibits AR signaling in prostate cancer." (PMID 41020902, 2025). "The first cluster is composed of ZNF740, AR, and TBX5, which are implicated in prostate cancer." (PMID 40453647, 2025). "Understanding these molecular details is crucial, as targeted disruption of the CNPY2-MYLIP interface could effectively reduce AR levels in prostate cancer cells." (PMID 40001982, 2025). "For example, a combination of doxycycline and bicalutamide could target both the androgen receptor pathway and cell proliferation processes, potentially overcoming resistance mechanisms and improving clinical outcomes for patients with prostate cancer." (PMID 40284400, 2025). "For example, it promotes androgen receptor (AR) stability and tumor growth in prostate cancer." (PMID 40941002, 2025). "Among them, the androgen receptor (AR) is the most studied and best characterized signaling transducer and transcription factor acting in the prostate tissue, due to its relevance for reproductive biology and prostate cancer." (PMID 39633177, 2025). "AR gene amplifications primarily occur in response to androgen deprivation therapy and are observed in more than 50% of patients with castration-resistant prostate cancer." (PMID 38383885, 2025). "For instance, ARD1‐specific inhibitors or therapeutic strategies that interfere with AR –ARD1 interactions may be critical for the treatment of prostate cancer (PCa)." (PMID 40026288, 2025).
prostate carcinoma (continued). "On one hand the AR-depend bioactivity a benefit that may reduce side-effects and on the other hand, it limits potential treatment to AR expressing prostate cancer cells." (PMID 40072554, 2025). "However, the peptide had no such inhibitory effect in AR-negative prostate cancer cell lines, suggesting that the peptide can only inhibit the androgen receptor-dependent Src pathway in prostate cancer." (PMID 39917165, 2025). "Androgen Deprivation Therapy (ADT), a standard intervention for advanced Prostate Cancer (PCa), could effectively reduce androgen levels or block androgen receptor signaling, effectively suppressing tumor growth and progression." (PMID 40955046, 2025). "Similarly, NKX3.1 expression is still maintained throughout the course of the disease and metastatic spread, and in the AR-positive and AR-driven prostate cancer cell line models commonly employed in PCa research." (PMID 39858088, 2025). "In prostate cancer, AR signaling in stromal cells, initially high during prostate development, progressively decreases as cancer advances, correlating with worse clinical outcomes and a shift from androgen-dependent paracrine to autocrine pathways in cancer cells." (PMID 40356745, 2025). "In this study, we explored whether matrix stiffness plays a role in transcriptional regulation, chromatin state, or AR function in prostate cancer cells." (PMID 40115748, 2025). "Although immune evasion mechanisms following endocrine therapy may represent one of the AR-independent pathways leading to endocrine therapy resistance, the application of immunotherapy in prostate cancer remains limited." (PMID 41079787, 2025). "Moreover, we report that NXP800 inhibits the growth of AR-independent prostate cancer models, indicating that its antitumor activity is not only mediated through abrogation of AR signaling." (PMID 39787247, 2025). "Given the correlative role of the wnt pathway with AR and MYC, combination therapy with an AR inhibitor or a MYC inhibitor may be useful in the treatment of advanced prostate cancer in the future." (PMID 39917165, 2025). "This direct link of AR signaling to prostate cancer makes it a suitable therapeutic target, and androgen deprivation therapy remains the primary treatment option for advanced prostate cancer." (PMID 40356745, 2025). "Nonetheless, these screens identify AR as a key target in prostate cancer." (PMID 40405591, 2025). "In contrast to clinically licensed AR antagonists, ARD-61, a novel AR PROTAC, has been shown to efficiently promote on-target AR degradation, elicit more potent antiproliferative and proapoptotic effects, and reduce downstream AR target gene expression in prostate cancer cells." (PMID 40717128, 2025). "Overall, this highlights the importance of identifying more effective therapies, including non-AR–targeted options, to treat a broader spectrum of patients with prostate cancer, particularly those with advanced prostate cancer or metastatic castration-resistant prostate cancer (mCRPC)." (PMID 40627156, 2025). "Next generation ARPIs extend prostate cancer survival through increased selective pressure on AR." (PMID 41509338, 2025). "Similarly, in prostate cancer, the inhibition of the AR pathway activates changes in the FOXA2-dependent transcriptional pattern, driving the adeno-to-neuroendocrine transition, thereby causing castration resistance." (PMID 40032852, 2025). "In prostate cancer, GR may confer resistance to anti-androgen receptor therapies by bypassing AR blockade." (PMID 41188544, 2025). "Importantly, the pharmacological inhibition of TET enzymes and supplementation with S-adenosyl methionine were found to effectively suppress AR-independent prostate cancer growth." (PMID 39743630, 2025).
prostate carcinoma (continued). "The VISION trial investigated this approach by enrolling patients with metastatic castration-resistant prostate cancer who had previously received at least one androgen receptor pathway inhibitor and one or two taxane-based treatments, and who exhibited PSMA-positive [68Ga]Ga-PSMA-11 scans." (PMID 41300900, 2025). "Currently, the main targets of anti-prostate cancer targeted drugs include androgen receptor (AR) signaling pathway inhibitors (e.g., abiraterone, enzalutamide), which play a therapeutic role by blocking testosterone synthesis or competitively inhibiting androgen binding." (PMID 40422804, 2025). "AR expression is widespread in both primary and metastatic prostate cancer tissues." (PMID 40959108, 2025). "The androgen receptor was primarily responsible for prostate cancer." (PMID 39898116, 2025). "In prostate cancer, it was shown that AR can promote DNA repair through homologous recombination as its inhibition can mimic the loss-of-function of the breast cancer type 1 susceptibility protein (BRCA1) and confer cancer sensitivity to poly(ADP-ribose) polymerase 1 (PARP1) inhibitors." (PMID 40150035, 2025). "In prostate cancer research, particularly in CRPC, there may be unknown AR mutations that play significant roles in drug resistance." (PMID 40008000, 2025). "This previously unrecognized mechanism highlights the complexity of AR-mediated transcriptional repression in prostate cancer and suggests that targeting AR signaling may restore LTFe function, thereby enhancing ferroptosis sensitivity in CRPC." (PMID 40082405, 2025). "Three studies focused on the AR-positive prostate cancer cell line LNCaP." (PMID 41614805, 2025). "In addition to TERT, we found rare non-synonymous variants in three genes associated with decreased prostate cancer risk (ANO7, SPDL1 and AR), and three genes associated with increased risk (HOXB13, CHEK2 and BIK)." (PMID 39971927, 2025). "Curcumin consistently reduces AR levels and activity in prostate cancer cells." (PMID 41020902, 2025). "More comprehensive studies are needed to confirm whether potential FOXM1/MYBL2/YAP pathway is responsible for regulating AR activity in response to changes in ECM stiffness in prostate cancer." (PMID 40115748, 2025). "As a result of the reduction of MBOAT1/2 expression, cells become sensitive to ferroptosis, which may be useful in combination with estrogen receptor (ER) and androgen receptor (AR) antagonists in the therapy of selected breast and prostate cancers." (PMID 40872573, 2025). "Among its substrates, the AR protein stands out as a key player in prostate cancer pathogenesis." (PMID 40432836, 2025). "Prostate cancer (PCa) is driven by androgen receptor (AR) signaling." (PMID 40805121, 2025). "Indirect strategies are designed to interfere with AR function by modulating AR-associated transcriptional co-regulators, chromatin accessibility, and other regulatory proteins, such as splicing factors, that are critical for sustaining AR-driven gene expression in prostate cancer." (PMID 41374958, 2025). "The importance of androgen receptor (AR) signaling in regulating the growth and survival of prostate cancer cells cannot be overstated, making androgen deprivation therapy (ADT), which targets this pathway, a cornerstone in the management of both early-stage and metastatic PCa." (PMID 40956849, 2025). "The androgen receptor (AR) is a major therapeutic target for aggressive prostate cancer." (PMID 39964832, 2025). "Moreover, it was shown that EGCG can modulate expression levels of PSA and AR transcription activity in LNCaP prostate cancer cells." (PMID 40336533, 2025). "Moreover, prostate cancer cells often exhibit AR-dependent modulation of glucose metabolism, with the androgen receptor (AR) promoting glucose transporter 1 (GLUT1) expression to increase glucose uptake." (PMID 41281744, 2025).
prostate carcinoma (continued). "Thus, finding and developing highly effective AR-targeted antagonists that combat resistance for the endocrine treatment of prostate cancer is an urgent need." (PMID 40224223, 2025). "In addition, we demonstrate that NXP800 reduces HSP72 expression and decreases AR signaling, reduces AR and AR-V7 protein expression as well as their DNA binding and transactivation, and also inhibits the growth of treatment-resistant prostate cancer models." (PMID 39787247, 2025). "The AR antagonist, bicalutamide, has been approved by the US Food and Drug Administration in combination with luteinizing hormone–releasing hormone therapy for the treatment of advanced prostate cancer." (PMID 40118451, 2025). "The most frequently requested medications included Androgen Receptor Pathway Inhibitors in 2,470 patients, which corresponded to approximately 88.9% of the demand for drugs and 78.8% of all treatment demands for patients with prostate cancer." (PMID 41092154, 2025). "AR splice variants that encode an AR protein lacking the ligand binding domain have emerged as potential drivers of prostate carcinoma resistance to AR-directed therapy." (PMID 40956611, 2025). "The clinically significant nature of prostate cancer has led to the discovery and development of several anti-androgen and AR-targeted therapies, altogether deepening the knowledge of AR-mediated action in prostate cells and its involvement in cell cycling and mitosis." (PMID 40269952, 2025). "CRELD2 may also mediate tumor angiogenesis and serve as a novel androgen receptor target in prostate cancer." (PMID 39869369, 2025). "Androgen receptor (AR) signaling plays a crucial role in modulating lipid metabolic processes, such as steroidogenesis and β-oxidation, thereby promoting the progression of prostate cancer in a hormone-dependent manner." (PMID 41009695, 2025). "Moreover, it was found that inhibition of AR is considered a potent target in prostate cancer therapy." (PMID 40336533, 2025). "Previous work in prostate cancer cells indicated that PAD2 regulates AR expression and signaling." (PMID 41226560, 2025). "It has been shown that AR activation can regulate a network of DNA repair genes in prostate cancer." (PMID 40940753, 2025). "Sulforaphane from cruciferous vegetables may reduce prostate cancer risk by inhibiting HDAC6 and androgen receptor signalling." (PMID 39778006, 2025). "The androgen receptor (AR) signaling axis is regarded as the key driver of prostate cancer (PCa)." (PMID 42004222, 2025). "In addition to AR signaling and genetic alterations, other factors such as inflammation and epigenetics play important roles in the pathophysiology of prostate cancer." (PMID 40356745, 2025). "The androgen receptor (AR) binds testosterone mediating gene expression for sexual, somatic, and behavioral functions and is involved in various conditions, including androgen insensitivity syndrome and prostate cancer." (PMID 41443423, 2025). "Here, we investigated whether matrix stiffness influences prostate cancer progression, transcriptional regulation, chromatin state, and AR function in AR-positive prostate cancer cells under varying ECM stiffness conditions." (PMID 40115748, 2025). "Although studies have demonstrated the utility of monitoring RNA transcripts from PSMA, PCA3, and AR genes for prostate cancer diagnosis, relying solely on these biomarkers may be limiting." (PMID 39859417, 2025). "In both hormone-dependent breast and prostate cancers, FOXA1 forms a triumvirate with a GATA protein and an NR (GATA3 and ER in breast cancer; GATA2 and AR in prostate cancer) and is the foundational protein in these cancers due to its ability to create new enhancer elements." (PMID 41168397, 2025).
prostate carcinoma (continued). "Studies on the influence of MCP inhibitors and the role of glutamine metabolism in cell proliferation and metabolism of prostate cancer cells suggest that there are fundamental differences in the metabolic characteristics of AR-positive and AR-negative prostate cancer." (PMID 40489535, 2025). "In addition, the androgen receptor (AR) is responsible for prostate cancer cell survival, with its activation being a powerful promoter for tumorigenesis." (PMID 40491606, 2025). "Consequently, the interaction between AR and YAP constitutes a critical regulatory axis in cellular processes associated with prostate cancer, playing a vital role in the progression and metastasis of the disease." (PMID 39963114, 2025). "Both the Brg1 and AR proteins are pro-oncogenes in prostate cancer, and thus, OTUD6A could promote the proliferation of prostate cancer cells by deubiquitinating and stabilizing the brahma-related gene 1 (Brg1) and androgen receptor (AR) proteins." (PMID 41050073, 2025). "However, despite initial responses to ADT, most prostate cancers eventually progress to a more aggressive, castration-resistant state, where AR signaling remains a driving force behind tumor growth." (PMID 40432836, 2025). "However, one study indirectly shows that degradation of TOMM20 by androgen receptor antagonists leads to increased ROS production in prostate cancer cells, contributing to drug resistance." (PMID 39996379, 2025). "For instance, ARV‐110 reduced androgen receptor abundance in resistant prostate cancer models." (PMID 39898116, 2025). "Taken together, these findings demonstrate that CMV inhibition can attenuate androgen signaling in CRPC and imply that CMV inhibition may have additive effects to androgen receptor‐targeting pharmaceutical compounds in CMV+ prostate cancer." (PMID 40493023, 2025). "Therefore, unraveling the molecular underpinnings and developing appropriate therapeutic strategies for AR-independent prostate cancer are urgently needed." (PMID 39743630, 2025). "Having determined that NXP800 activates the UPR gene signature and blocks AR and E2F activity in multiple prostate cancer models, we investigated whether, at least in part, these molecular mechanisms could be linked." (PMID 39787247, 2025). "Hyper-activation of this pathway, often driven by loss of the tumor suppressor phosphatase and tensin homolog (PTEN) or AKT and mTOR dysregulation, facilitates the transition to castration-resistant prostate cancer by compensating for suppression of androgen receptor signaling." (PMID 41375042, 2025). "These medications target the AR signaling that drives prostate cancer growth." (PMID 41235005, 2025). "The androgen receptor (AR) is the main driver of nearly all prostate cancer (PCa)." (PMID 40833121, 2025). "AR signaling continues to be active, promoting the survival and growth of prostate cancer cells." (PMID 40356745, 2025). "Collectively, these AR-dependent mechanisms enable prostate cancer cells to resist androgen deprivation and continue to proliferate, highlighting the complexity of CRPC biology and the need for advanced therapeutic strategies that can effectively overcome or bypass AR signaling pathways." (PMID 41235005, 2025). "The androgen receptor (AR) is the primary transcription factor driving prostate tumorigenesis and disease progression, making it a central therapeutic target throughout most stages of prostate cancer, including castration-resistant prostate cancer (CRPC)." (PMID 41237749, 2025). "As a result, therapies targeting the AR pathway, such as next-generation AR antagonists and agents that inhibit androgen biosynthesis, remain the cornerstone of CRPC management, emphasizing the clinical importance of AR in the resistance and evolution of advanced prostate cancer." (PMID 41235005, 2025).